AKAP4 (A-kinase anchoring protein 4)
Diseases named in the same sentence as AKAP4 in open-access papers (continued):
Sharing a sentence is not in itself a finding about the gene and the disease.
tumor (continued). "As a component of AKAP4, FSIP1 may play a role in tumor biology and thus may be a target for cancer immunotherapy." (PMID 35692888, 2022). "In addition, FSIP1 can bind to and activate cancer/testis antigen proteins (including CABYR, SPA17, AKAP3, AKAP4, and ROPN1) in the fibrous sheath in tumor cells, in turn promoting cancer progression." (PMID 28086239, 2017). "AKAP4 expression increases significantly with tumor stage, but independent of age, gender, smoking history or cancer subtype." (PMID 26160834, 2015). "More general tumor antigens, like MUC-1, AKAP-4, and NY-ESO-1, can also be found in PCa and might be candidates for immunotherapeutic interventions." (PMID 24834066, 2014). "Additionally, we showed that AKAP-4 was expressed in the same tissues at the transcriptional and protein levels in tumor-bearing animals, but absent in healthy controls." (PMID 21923911, 2011). "AKAP-4 protein was detected by Western blot analysis in MM cell lines, primary MM cells, bone marrow, peripheral blood and spleens of tumor-bearing mice, but not in tumor-free mice (healthy controls)." (PMID 21923911, 2011). "+ or − indicates the tumor cells were positive or negative for the indicated CTA (SP17, AKAP4, or PTTG1), or for the CTA-specific IgG (n.a.= serum not available)." (PMID 25739119, 2015).
cancer (17 papers, 2013 to 2025). A tumor composed of atypical neoplastic, often pleomorphic cells that invade other tissues. "Humoral response against AKAP4 was found to be strongly associated with cancer patients as compared to the healthy control donor’s samples (P<0.001, Pearson’s Chi-square test)." (PMID 23451156, 2013). "The analysis identified that AKAP4 expression is significantly associated only with cancer stage." (PMID 26160834, 2015). "High expression of AKAP4 and the biofunction of AKAP4 in the development of malignant tumors have been widely reported." (PMID 35253625, 2022). "Cancer testis (CT) antigen is one of the hotspots of developing therapeutic targets, with A-kinase anchor protein 4 (AKAP4) being seen as a novel CT antigen." (PMID 36551152, 2022). "AKAP4 is one of the scaffold proteins associated with cAMP-dependent PKA and is highly expressed in various types of cancers." (PMID 35692888, 2022). "Compared to para-carcinoma tissues, AKAP4 was significantly upregulated in clinical NSCLC tissues (**p < 0.01, vs. para-carcinoma tissues)." (PMID 35253625, 2022). "Effects of AKAP4 ablation on various malignant properties of cancer cells were investigated in A10 and Caov-3 cells." (PMID 28881798, 2017). "A-kinase anchor protein 4 (AKAP4), a unique cancer testis (CT) antigen has been shown to be associated with various malignant properties of cancer cells." (PMID 28881798, 2017). "In this study, we examined the involvement of AKAP4 in various malignant properties at phenotype and molecular level of cancer cells." (PMID 26590805, 2015). "Ablation of AKAP4 apparently has multiple effects at molecular level in various malignant properties of the cancer cells including reduction in colony formation ability, expression of EMT molecules and growth arrest of cells (senescence)." (PMID 26590805, 2015). "All cancer cell lines showed higher levels of AKAP4 expression compared to normal colon epithelial cells." (PMID 26590805, 2015). "The involvement of AKAP4 is suggestive of its pivotal role in tumorigenesis and holds promise to serve as a biomarker for better clinical management of cancer patients." (PMID 23451156, 2013). "AKAP4, a cancer and testis antigen, was detected in PC3 cells, though protein phosphatase 1 γ2 was absent, suggesting MSS1 may target other protein phosphatase 1 isoforms." (PMID 41092058, 2025). "AKAP4 is an oncogene discovered in some malignant tumors, and its molecular function of AKAP4 in NSCLC is unknown." (PMID 35253625, 2022). "AKAP4 is highly expressed in a variety of cancers, and the regulatory subunit PKAI of PKA has also been shown to play important roles in promoting the proliferation and transformation of tumors and the generation of immunosuppressive microenvironments in the tumor microenvironment (TME)." (PMID 34113648, 2021). "In present investigation, our data revealed that ROS may be a trigger and initiator, leading to caspase activation and cell death in AKAP4 ablated cancer cells." (PMID 28881798, 2017). "However, mechanism of AKAP4 anchored PKA signaling favoring acquisition of metastatic behavior of cancer cells still requires further studies to provide better insight." (PMID 28881798, 2017). "Multiple studies have shown that AKAP4 is strongly expressed in several types of cancer." (PMID 25826084, 2015). "In present investigation, we assessed the involvement of AKAP4 in cascades of various pathways contributing towards the malignant properties of cancer cells which may shed light on AKAP4 as a novel therapeutic target." (PMID 26590805, 2015). "Further, we also found the down regulation of anti-apoptotic molecules BCL-2, Bcl-xL, cIAP2, XIAP, Axin2 and Survivin in the AKAP4-depleted CRC cells indicating that AKAP4 may be potential therapeutic target in cancer management." (PMID 26590805, 2015).
cancer (continued). "Similarly, in different grades, anti-AKAP4 antibodies were detected in majority of grade 1 (77%), grade 2 (81%) and grade 3 (88%) cancer patients with mean titers of 0.66±0.05, 0.80±0.08, and 0.63±0.08 respectively." (PMID 23451156, 2013). "Moreover, detection of humoral response against AKAP4 represents a better and minimal invasive method of diagnosis from the sera of cancer patients." (PMID 23451156, 2013). "Moreover, AKAP4 expression was recently validated by employing microarray gene expression analysis that revealed restricted AKAP4 expression only in testis and in various cancer cells." (PMID 23451156, 2013). "Among these proteins, AKAP4 and AKAP9 have been extensively studied as cancer-promoting factors, whereas AKAP12 and recently AKAP13 have been shown to play the opposite role, although their mechanism of action has not been studied in depth." (PMID 36203781, 2022). "Current evidence demonstrated that cancer testis antigens (CTA) such as pituitary tumor transforming gene 1 (PTTG1), A-kinase anchor protein 4 (AKAP4), and sperm protein 17 (SP17) are potential immunotherapeutic targets in NSCLC." (PMID 35463817, 2022). "Among them, AKAP4 and AKAP9 have been widely studied as cancer-promoting factors, while AKAP12 have proved to play the opposite role." (PMID 34722307, 2021). "We found that SP17, AKAP4 and PTTG1 are aberrantly expressed in cancer samples, compared to normal lung cell lines and tissues." (PMID 25739119, 2015). "Thus, AKAP4 may be used as therapeutic target for cancer treatment." (PMID 26590805, 2015). "In addition, onset of apoptosis was also observed in AKAP4 ablated cells due to increased expression of various pro-apoptotic molecules and decreased expression of anti-apoptotic proteins indicating that AKAP4 may be a new therapeutic target for cancer treatment." (PMID 28881798, 2017). "Because expression of AKAP4 is normally confined to testis the background expression in cancer free controls is essentially negative." (PMID 26160834, 2015). "As a component of AKAP4, FSIP1 may play a role in tumorigenesis and could therefore be a target for cancer immunotherapy." (PMID 25826084, 2015). "The AKAP4 protein expression in majority of cancer patients irrespective of their clinical stages and histopathological grades indicates that AKAP4 may have a potential role in disease progression." (PMID 23451156, 2013). "Despite a lack of studies on the relationship between FSIP2 and cancer, FSIP2 has been shown to not only an important part of AKAP4 but to also influence the function of PKA by docking to AKAP4." (PMID 34113648, 2021).
lung (1 paper, 2015). "We validated AKAP4 as a highly accurate biomarker in a cohort of 264 NSCLCs and 135 controls from 2 different sites including a subset of controls with high risk lung nodules." (PMID 26160834, 2015).
AKAP4 also shares sentences with these, for which no sentence is quoted: cervical cancer (2 papers); multiple myeloma (2); ovarian serous carcinoma (2); adenocarcinoma (1); ductal carcinoma (1); ductal carcinoma in situ (1); dysplasia of (1); esophageal squamous cell carcinoma (1); glioma (1); infection (1); infiltrating ductal carcinoma (1); lung adenocarcinoma (1); lung squamous cell carcinomas (1); reproductive diseases (1); seminoma (1); systemic lupus erythematosus (1); teratozoospermia (1).